PRRT2 (proline rich transmembrane protein 2)
Diseases named in the same sentence as PRRT2 in open-access papers (continued):
Sharing a sentence is not in itself a finding about the gene and the disease.
paroxysmal kinesigenic dyskinesia (continued). "We screened PRRT2 copy number variants using the AccuCopyTM method in 29 patients with paroxysmal kinesigenic dyskinesia with negative PRRT2 point and frameshift mutations." (PMID 30307717, 2018). "Furthermore, very recently the genetic heterogeneity of HM phenotype has been broadened with the PRRT2 gene, previously related to paroxysmal kinesigenic dyskinesia and other episodic disorders." (PMID 24498617, 2013). "PRRT2 is associated with familial infantile convulsions with paroxysmal choreoathetosis (MIM #602066), episodic kinesigenic dyskinesia 1 (MIM #128200), and benign familial infantile seizures 2 (MIM #605751); and the penetrance of episodic kinesigenic dyskinesia 1 is estimated to be 60%–90%." (PMID 34858471, 2021). "Mutations in proline-rich transmembrane protein 2 (PRRT2) have been recently identified as the leading cause of a clinically heterogeneous group of neurological disorders sharing a paroxysmal nature, including paroxysmal kinesigenic dyskinesia and benign familial infantile seizures." (PMID 33056987, 2020). "The PRRT2 gene of infantile epileptic patients with a family history of infantile convulsions or paroxysmal kinesigenic dyskinesia(PKD) could be detected by sanger sequencing and a biomarker to select antiepileptic drugs which play the mechanism of the sodium channel blockers could be utilized." (PMID 32246320, 2020). "The aim of this study is to determine whether copy number variant of PRRT2 gene is another potential pathogenic mechanism in the patients with paroxysmal kinesigenic dyskinesia with negative PRRT2 point and frameshift mutations." (PMID 30307717, 2018). "This study explored the topological characteristics of brain white matter structural networks in patients with Paroxysmal Kinesigenic Dyskinesia (PKD), and the potential influence of the brain network stability gene PRRT2 on the structural connectome in PKD." (PMID 32592228, 2020). "Most commonly testing of PRRT2 for paroxysmal kinesigenic dyskinesia (PKD), PNKD in paroxysmal non-kinesigenic dyskinesia (PNKD) or SLC2A1 in paroxysmal-exercised induced dyskinesia (PED)." (PMID 34177764, 2021).
benign familial infantile epilepsy (42 papers, 2012 to 2026). A genetic epileptic syndrome characterized by the occurrence of afebrile repeated seizures in healthy infants, between the third and eighth month of life. "At an early age, the PRRT2 mutations have been associated to benign familial infantile epilepsy, benign infantile epilepsy, and benign myoclonus of early infancy." (PMID 31801583, 2019). "The single PRRT2 variant (c.649dupC) was found in five patients with benign familial infantile epilepsy." (PMID 31572294, 2019). "PRRT2 has been recently identified as the cause of three clinical entities: benign familial infantile epilepsy (BFIE), infantile convulsions with choreoathetosis (ICCA) syndrome, and PKD27." (PMID 27173777, 2016). "Mutations in PRRT2, associated with benign familial infantile epilepsy, have also been implicated in hemiplegic migraine and may warrant seizure prophylaxis in addition to migraine prevention." (PMID 41552155, 2025). "This is due only in part to the early start of seizures in DEE but also to the infantile manifestation of focal seizures in benign familial infantile epilepsies, which may be caused by variants in the PRRT2, KCNQ2, SCN2A, like in our cohort." (PMID 38328757, 2023). "In addition to PKD patients, PRRT2 mutations have also been identified in patients with infantile convulsions with paroxysmal choreoathetosis, benign familial infantile epilepsy, migraine or episodic ataxia." (PMID 31722684, 2019). "Mutations in PRRT2 are also associated with several other neurological diseases, including benign familial infantile epilepsy (BFIE), infantile seizure syndrome with choreoathetosis (ICCA) and paroxysmal kinesigenic dyskinesia (PKD)." (PMID 36800925, 2023). "Nucleotide alterations in the gene encoding proline-rich transmembrane protein 2 (PRRT2) have been identified in most patients with benign partial epilepsies in infancy (BPEI)/benign familial infantile epilepsy (BFIE)." (PMID 25794116, 2015). "Mutations in proline-rich transmembrane protein 2 (PRRT2), which affects neurotransmitter release, are linked to both migraine and benign familial infantile seizures." (PMID 40149800, 2025). "Benign familial infantile epilepsy is a well-known phenotype of PRRT2 (OMIM 605751) in addition to paroxysmal dyskinesia (OMIM 128200)." (PMID 31572294, 2019). "Mutations in PRRT2, which influences Ca2+-dependent synchronous release via interaction with SYT1, lead to benign infantile familial seizures, paroxysmal movement disorders and intellectual disability." (PMID 30107533, 2018). "More recently, PRRT2 mutations were also discovered in Infantile Convulsions and Choreoathetosis (ICCA) and Benign Familial Infantile Epilepsy (BFIE)." (PMID 27449084, 2016). "Further investigations have shown that infantile convulsions with choreoathetosis (ICCA) syndrome and benign familial infantile epilepsy (BFIE) are also induced by PRRT2 mutations." (PMID 26621826, 2015). "The PRRT2 c.649delC variant has been associated with benign familial infantile seizures and episodic kinesigenic dyskinesia, with or without infantile seizures, although there is growing evidence of incomplete penetrance." (PMID 40126231, 2025). "PRRT2 mutations were first linked to PKD in 2011, and this gene was later found to cause also benign familial infantile seizures (BFIS) and infantile convulsions with choreoathetosis (ICCA) syndrome, leading to consider PRRT2-related paroxysmal disorders as a continuous phenotypic spectrum." (PMID 32443735, 2020).
migraine (27 papers, 2013 to 2025). "Genome-wide association analyses of migraine and its subtypes identify new susceptibility loci, including rare variants with large effects implicating PRRT2, SCN11A and KCNK5." (PMID 37884687, 2023). "In a recent study, migraine occurred as a concomitant diagnosis of BFIE in 10% of PRRT2-associated patients, suggesting an increased risk for migraine in younger patients with PRRT2-associated BFIE." (PMID 34041212, 2021). "This difference further confirms an association of migraine with PRRT2 and underlines an elevated risk for migraine in patients presenting with BFIS in association with PRRT2." (PMID 33126500, 2020). "The phenotypes associated with PRRT2 mutations included a high frequency of migraine and hemiplegic migraine." (PMID 26598494, 2015). "This suggests that PRRT2-related disorders may involve a shared pathogenic mechanism that links seizures, movement disorders, and migraines to synaptic dysfunction." (PMID 39596051, 2024). "Though limited, these studies indicate that mutations in the PRRT2 gene may be a genetic mechanism for hemiplegic migraine; however, further studies are needed to thoroughly examine the role of this gene." (PMID 38731230, 2024). "This applies to the four canonical FHM genes (CACNA1A, ATP1A2, SCN1A, and PRRT2), as well as the other genes reported to cause syndromes which may present with migraine." (PMID 36044383, 2022). "However, given the high prevalence of migraine in the general population, a specific association with PRRT2 mutations deserves further studies." (PMID 33746883, 2021). "Thus, a PRRT2 mutation may increase the risk of hemiplegic migraine as “add-on” mutation but it seems unlikely that PRRT2 is the FHM4 gene." (PMID 32503413, 2020). "A genetic variant in the PRRT2 gene (NM_145239.3:c.938C > T; p.Ala313Val) was discovered via a WES family analysis in a 40-year-old male patient suffering from migraine with aura." (PMID 38731230, 2024). "Although CSD is the putative electrophysiological process responsible for the generation of migraine aura, patients with PRRT2‐related PKD also often report auras (or a sense of impending attacks) prior to dyskinetic events." (PMID 37288166, 2023). "In recent years several genes have been put forward as possible hemiplegic migraine genes (i.e. PRRT2, SLC1A3 and SLC4A4), but evaluation of available data should cast doubt on such claims." (PMID 32503413, 2020). "Familial hemiplegic migraine type 1 (FHM1) is a form of migraine with aura caused by heterozygous mutations in 4 genes: CACNA1A, ATP1A2, SNC1A and PRRT2, but further heterogeneity is expected." (PMID 30167989, 2018). "As far as we know, c.1023A > T is the first reported mutation in exon 4 of PRRT2. c.649delC was previously reported in PKD, ICCA and hemiplegic migraine families, but we further detected it in BFIE-only families." (PMID 24370076, 2013). "In addition, 5% of PRRT2 patients display other disorders, such as episodic ataxia, hemiplegic migraine, developmental delay, and intellectual disability." (PMID 36958475, 2023). "So the presence of such PRRT2 mutation does not suffice to cause hemiplegic migraine in the Mendelian fashion seen with the three hemiplegic migraine genes." (PMID 32503413, 2020). "Interestingly, among PRRT2 mutation carriers, out of 1444 patients, 32 patients had migraine with aura, 36 patients had migraine without aura, and 34 patients had HM." (PMID 38273253, 2024). "Additionally, patients with PRRT2 variants may exhibit a broader spectrum of non-epileptic phenotypes, including paroxysmal dyskinesias and migraine." (PMID 39596051, 2024). "Therefore, the association of migraine with PRRT2 mutation may not be coincidental." (PMID 24370076, 2013). "The phenotype of migraine (with or without aura) has been reported in BFIE, PKD or ICCA families with a PRRT2 mutation." (PMID 24370076, 2013).
paroxysmal dyskinesia (25 papers, 2012 to 2025). Paroxysmal dyskinesia (PD) is a rare heterogenous group of movement disorders manifesting as abnormal involuntary movements that recur episodically and last only a brief time. "In earlier reports, most patients carried mutations in paroxysmal dyskinesia-specific genes such as PRRT2, PNKD and SLC2A1, typically associated with isolated phenotypes and favourable treatment responses." (PMID 40943684, 2025). "The constitutive PRRT2 KO mouse recapitulated many of the phenotypic traits of human PRRT2-linked disorders, including paroxysmal dyskinesias and higher seizure propensity." (PMID 31940887, 2020). "It has been confirmed that PRRT2 mutations can cause infantile convulsions and paroxysmal dyskinesia alone or in various combinations besides PKD." (PMID 26621826, 2015). "Sanger sequencing was used to analyze all four PRRT2 exons for sequence variants in 13 probands (9 Caucasian, 1 Caucasian-Thai, 1 Vietnamese and 2 African-American) with some form of paroxysmal dyskinesia." (PMID 22985072, 2012). "Pathogenic variants of PRRT2 are associated with a large spectrum of familial neurological disorders: PRRT2 is primarily associated with paroxysmal dyskinesia (PKD) but also hemiplegic migraine (HM), infantile convulsions and choreoathetosis (ICCA) and benign sporadic and familial seizures (BFIS)." (PMID 35350397, 2022). "Furthermore, we demonstrate that paroxysmal dyskinesia-associated mutations in PRRT2 disrupt this SNARE-modulatory function and with efficiencies corresponding to the severity of the disease phenotype." (PMID 29346777, 2018). "To expand the genotypic spectrum of PRRT2 mutations and examine the role of PRRT2 in other racial groups, we report the clinical and genetic data for 13 probands with paroxysmal dyskinesias including 1 Vietnamese, 1 mixed Caucasian-Thai and 2 African-Americans." (PMID 22985072, 2012). "Interestingly, two of these patients had paroxysmal dyskinesia and two patients exhibited seizures, suggesting that increased PRRT2 gene dosage alone may be able to cause neurological symptoms in humans." (PMID 36808153, 2023). "In terms of overlap with other syndromes, in this series a family [F2] with infantile convulsions and paroxysmal choreoathetosis (ICCA) was found, an association commonly observed in PRRT2 mutations." (PMID 31186958, 2019). "In contrast with previous studies, only a small proportion of patients had dyskinesia (5.3%) and no patient was identified carrying the PRRT2 mutation which is a well-known, most-common cause of the paroxysmal dyskinesia." (PMID 35719373, 2022). "PRRT2 is a candidate gene for ASD since homozygote mutations are associated with intellectual disability and heterozygote mutations cause benign infantile seizures, paroxysmal dyskinesia, or hemiplegic migraine." (PMID 24594579, 2014). "We performed a single gene test for PRRT2 for patients with paroxysmal dyskinesia who were not eligible for WES, which may be a reason for these results." (PMID 35719373, 2022).
hemiplegic migraine (19 papers, 2013 to 2026). "Other rare phenotypes, including seizures, ictal ataxia, and hemiplegic migraine, have also been reported, suggesting significant phenotypic heterogeneity resulting from PRRT2 mutations." (PMID 37228410, 2023). "Recently, mutations in the proline-rich transmembrane protein 2 gene (PRRT2) have been shown to be associated with hemiplegic migraine." (PMID 24041236, 2013). "In addition, several studies have reported that other disorders, including hemiplegic migraine and episodic ataxia, could be a PRRT2-associated phenotype." (PMID 34041212, 2021). "Other rare phenotypes include hemiplegic migraine (HM) and sporadic benign infant epilepsy (BIE), suggesting phenotypic heterogeneity in PRRT2 mutations." (PMID 32237035, 2020). "PRRT2 is the major causative gene of PKD, BFIE, and ICCA, and is also responsible for several familial or sporadic cases with paroxysmal non-kinesigenic dyskinesia (PNKD), paroxysmal exercised-induced dyskinesia (PED), sporadic BIE, and hemiplegic migraine (HM)." (PMID 24370076, 2013).
episodic ataxia (18 papers, 2014 to 2023). "A handful of cases are reported with homozygous PRRT2 mutations and a severe phenotype with episodic ataxia, intellectual disability, and infantile seizures." (PMID 37008993, 2023). "Patients with biallelic mutations in PRRT2 have been reported to have a more severe phenotype with including different seizure types, status epilepticus, episodic ataxia, and PKD." (PMID 33833732, 2021). "Mutations in PRRT2 have also been associated with other paroxysmal disorders, such as episodic ataxia, and hemiplegic migraine." (PMID 33833732, 2021). "Two PRRT2 mutations were in familial hemiplegic migraine or episodic ataxia, one SLC2A1 family had episodic ataxia and one PNKD family had familial hemiplegic migraine alone." (PMID 26598494, 2015). "A family with episodic ataxia and one with familial hemiplegic migraine alone were identified with PRRT2 mutations." (PMID 26598494, 2015). "In rare instances, PRRT2 mutations can also cause episodic ataxia." (PMID 33833732, 2021). "One girl with a bi-allelic variant in PRRT2 presented with episodic ataxia." (PMID 33126500, 2020). "We present additional evidence for a role of PRRT2 in early-onset movement disorders, as well as childhood-onset episodic ataxia." (PMID 33126500, 2020). "In 1 large study of 374 PRRT2-positive patients, episodic ataxia was only occasionally reported." (PMID 37008993, 2023). "One girl with bi-allelic variants in PRRT2 presented with episodic ataxia (EA) and non-epileptic myoclonus after minor head trauma (see: episodic ataxia with myoclonus after minor head trauma)." (PMID 33126500, 2020). "In the episodic ataxia cohort, one family was identified with a mutation in the PRRT2 gene, one with a defect in the SLC2A1 gene and two familial hemiplegic migraine families were identified, one with a PRRT2 mutation and one with a novel PNKD mutation." (PMID 26598494, 2015). "Due to these nonepileptic events, molecular testing for episodic ataxia panel (CACNA1A, CACNB4, KCNA1, PNKD, PRRT2, SLAC1A3, VAMP1) was requested, and this came back normal." (PMID 37469362, 2023).
Intellectual disability (17 papers, 2014 to 2025). "Patients bearing homozygous or compound heterozygous mutations in PRRT2 show a severe encephalopathic phenotype, with paroxysmal dyskinesias, unusually prolonged ataxia attacks, seizures, and intellectual disability." (PMID 36958475, 2023). "Single reports on bi-allelic loss of PRRT2 have been described in more severe phenotypes of epileptic disorders with intellectual disability, or combinations of paroxysmal disorders, suggesting a gene dosage effect." (PMID 33126500, 2020). "Meanwhile, homozygous PRRT2 mutations have been more frequently associated with intellectual disabilities." (PMID 25915028, 2015). "According to the literature, 52.4% of patients carrying homozygous PRRT2 truncation mutations have intellectual disabilities, whereas only 0.6% of patients with heterozygous mutations have these symptoms, suggesting a gene‐dosage‐dependence of PRRT2 in intellectual development." (PMID 34997978, 2022). "However, it should be noted that, in the context of 16p11.2 deletions, phenotype severity might be owing to deletion of adjacent genes and, therefore, the association of intellectual disability and heterozygous PRRT2 mutations requires additional confirmation." (PMID 33746883, 2021). "Beyond paroxysmal neurological disorders, there is preliminary evidence that heterozygous PRRT2 mutations might also cause intellectual disability and/or developmental delay, a suggestion supported by their invariable presence in cases with 16p11.2 deletions and homozygous PRRT2 mutations." (PMID 33746883, 2021). "Besides, homozygous PRRT2 mutations have been mainly associated with intellectual disabilities." (PMID 27449084, 2016). "Medically refractory genetic generalized epilepsy and intellectual disability were diagnosed in 1 child with a whole-gene PRRT2 deletion and 16p11.2 microdeletion." (PMID 40401013, 2025). "Mutations in PRRT2 associated with a range of neurological disorders in humans (including paraoxysmal kinesigenic dyskinia (PKD), infantile epilepsy and convulsions, hemiplagic migraines, ataxia, and intellectual disability) indicated that PRRT2 plays important roles in neurotransmission." (PMID 39653855, 2025). "Two patients with PRRT2 variants also showed intellectual disability and behavioral problems that could not be classified as self-limited or benign." (PMID 31572294, 2019). "In conclusion, this study identified two de novo 16p11.2 deletions involving PRRT2 in patients with PKD but without intellectual disability, extending the phenotype of 16p11.2 deletions to typical PKD." (PMID 30307717, 2018).